MIR509-3 (microRNA 509-3)
Synonyms: hsa-mir-509-3; MIRN509-3; mir-509-3
Gene: MicroRNA gene on chromosome X (147,259,652 to 147,259,726, reverse strand). Ensembl gene ENSG00000212014.
Homologues: Orthologues: macaque mml-mir-509-1 (92% identical), macaque mml-mir-509-2 (92% identical), mouse Mir509 (73% identical), rabbit ocu-mir-506 (47% identical). Paralogues in human: MIR509-1 (99% identical), MIR514A1 (81% identical), MIR514A2 (80% identical), MIR514A3 (80% identical), MIR514B (77% identical), MIR507 (57% identical), MIR513B (57% identical), MIR506 (56% identical), MIR513A2 (56% identical).